APOB (apolipoprotein B)
Diseases named in the same sentence as APOB in open-access papers (continued):
Sharing a sentence is not in itself a finding about the gene and the disease.
ischemic stroke (continued). "We also found that the risk of individuals carrying the ApoB rs693 “AA-AG” genotype had Ischemic Stroke risk of 1.52-fold of carrying “GG” genotype in the dominant model." (PMID 29416768, 2018). "In conclusion, our study revealed that ApoB rs1042034, rs693 and rs673548 mutation were significantly associations with the hereditary susceptibility of Ischemic stroke." (PMID 29416768, 2018). "In the allele model, ApoB rs1042034 “T” allele and rs673548 “G” allele increased the risk of the Ischemic Stroke (rs1042034: OR=1.29, 95%CI: 1.02-1.63, p=0.030; rs673548: OR=1.28, 95%CI: 1.02-1.62, p=0.034)." (PMID 29416768, 2018). "We investigated the effects of ApoB gene on susceptibility to Ischemic stroke in Chinese male population, and found that rs1042034, rs693 and rs673548 in ApoB gene increased the risk of Ischemic stroke in Chinese Han population." (PMID 29416768, 2018). "Logistic regression analysis found that ApoB rs1042034 and rs673548 increased the risk of Ischemic Stroke in the log-additive model, the odds of having Ischemic Stroke would be 1.28-fold and 1.27-fold with the variant allele, respectively." (PMID 29416768, 2018). "We also found that ApoB rs1042034, a missense resulting in Ser4338Asn, increased the risk of Ischemic stroke, the odds of having Ischemic Stroke would be 1.28-fold with the variant allele." (PMID 29416768, 2018). "So, the purpose of our research was to explore the effect of ApoB gene polymorphism on the genetic susceptibility to Ischemic Stroke in Chinese Han male population." (PMID 29416768, 2018). "To date, several independent studies suggest that APOA1, APOA5 and APOB levels are risk factors for ischemic stroke risk in Western populations." (PMID 28947988, 2017). "The minor allele “A” of rs693 in APOB was associated with an increased ischemic stroke risk in the additive model (OR = 1.583; 95 % CI = 1.045 - 2.397; p = 0.030) and dominant model (OR = 1.610; 95 % CI = 1.024 - 2.530; p = 0.039) respectively." (PMID 28947988, 2017). "The haplotype “TGAG” in APOB constructed by rs1042034, rs676210, rs693 and rs673548 in chromosome 2 was associated with an increased ischemic stroke risk (OR = 1.583; 95 % CI = 1.045 - 2.397; p = 0.031)." (PMID 28947988, 2017). "We therefore performed a case-control study to investigate the associations between single nucleotide polymorphisms (SNPs) in APOA1, APOA5 and APOB, and the risk of ischemic stroke in Chinese Han population." (PMID 28947988, 2017). "However, current smoking, ApoB, low ApoA1, male sex and education level of ≤ 9 years of schooling were preferentially associated with CE compared to ischemic stroke." (PMID 34772344, 2021). "The association of AA synthesis with IHD and ischemic stroke may be mediated by ApoB or LDL-C, but most likely by ApoB." (PMID 33924871, 2021). "Increase apoB/AI ratio has been demonstrated as an independent risk factor for ischemic stroke." (PMID 31479420, 2019). "As the apoB/AI ratio increased, the risk of suffering stenosis increased, which may raise the morbidity of ischemic stroke." (PMID 31479420, 2019). "Some studies found that elevated apoB level added the risk of Ischemic stroke." (PMID 29416768, 2018). "So, we speculate that ApoB influences the risk of occurrence of Ischemic Stroke by influencing the concentration of lipoprotein." (PMID 29416768, 2018). "However, little is known about the contribution of APOA1, APOA5 and APOB genes polymorphisms to ischemic stroke risk, especially in the Chinese Han population." (PMID 28947988, 2017). "Four SNPs of APOB gene significantly associated with the risk of ischemic stroke." (PMID 29245986, 2017). "A large prospective cohort study of women indicated a significantly elevated risk of first cardiovascular events, including ischemic stroke, among those at the extreme quintiles of all lipid parameters, including ApoA-I and ApoB, the major protein constituents of HDL and LDL, respectively." (PMID 20028534, 2009).
ischemic stroke (continued). "The polymorphisms of the ApoB gene may affect Ischemic Stroke occurrence." (PMID 29416768, 2018). "This study aimed to investigate the relationship of the serum apolipoprotein B (ApoB)/apolipoprotein A-I (ApoA-I) ratio with intracranial atherosclerotic stenosis (ICAS) in young patients with ischemic stroke." (PMID 42256577, 2026). "In a 2020 MR analysis, genetically elevated LDL-C and apoB were specifically tied to increased risk of large-artery stroke (LAS), while PCSK9-mediated LDL-C reduction showed protective effects across all ischemic stroke types." (PMID 40863347, 2025). "The increase in ApoB/ApoA1 was positively correlated with the incidence rate of ischemic stroke (the PFDR-values in the analyses of IVW, Weighted median, MR-PRESSO were all significantly less than 0.05)." (PMID 38310324, 2024). "The evidence provided by a Mendelian randomization study supports the suggestion that apolipoprotein B is a major feature of the etiologic basis of ischemic stroke, particularly in large-artery and small-vessel stroke." (PMID 38274879, 2023). "A similar approach has been used to show ApoB, LDL‐C, and triglycerides to be associated with ischemic stroke, large artery stroke, and small vessel stroke." (PMID 37243914, 2023). "For example, multivariable MR analyses on several lipids and lipoproteins highlighted the central role of apolipoprotein B compared to other lipids in ischemic stroke." (PMID 37804188, 2023). "A total of 163 patients aged 70 years were included, and an elevated ApoB/ApoA1 ratio was shown to be an independent predictor of ischemic stroke in people aged 70 years and older in a multivariate regression analysis." (PMID 38274879, 2023). "We analyzed the relationship between ApoB/ApoA-I ratio and ischemic stroke recurrence within 1 year." (PMID 38274879, 2023). "This study aimed to investigate the correlation of serum levels of apolipoprotein B 48, interleukin‐1β and Homocysteine with BMI in patients with ischemic stroke (IS)." (PMID 34492129, 2021). "A graded increase with increased apoB/apoA-1 ratio was also found for ischaemic stroke, CABG or PCI, CV mortality, and MACE and coronary intervention as a combined event." (PMID 34851955, 2021). "A significant association between the increase in the carotid arterial intima-media thickness and increased apoB/apoA-I levels was found in patients with ischemic stroke." (PMID 33153204, 2020). "Related to lipoprotein components, some polymorphisms of apoB, PAF-AH, and PON1 are also associated with high ischemic stroke risk." (PMID 33153204, 2020). "A previous South Korean study has demonstrated that an increased apoB/AI ratio was an independent predictor for intracranial atherosclerotic stenosis in ischemic stroke patients." (PMID 31479420, 2019). "Recent studies have identified several predisposing genes that are associated with ischemic stroke risk, including HDAC9, LTC4S, ALOX5, APOA1, APOB." (PMID 28947988, 2017). "Multivariate regression analysis adjusting for multiple ischemic stroke risk factors showed that the ApoB/ApoA1 ratio had a higher predictive value for ischemic stroke (OR: 2.33, 95% CI 1.80–3.00) than the non-HDL-C/HDL-C ratio (OR: 1.47, 95% CI 1.17–1.86)." (PMID 38274879, 2023). "In addition, the associations with female sex, lipid-lowering drugs, BMI, ApoB/ApoA1 ratio, ApoA1, and ApoB were different for PD versus coronary events and PD versus ischemic stroke." (PMID 36008425, 2022). "In multivariable MR, we assessed the association of AA synthesis with IHD and ischemic stroke adjusting for LDL-C or ApoB, but not both because they are highly correlated." (PMID 33924871, 2021). "Furthermore, in our study, we found that the ApoB/ApoA1 ratio and ethnicity had an additive interaction effect on first-ever ischaemic stroke (RERI 5.75, 95% CI 0.58 ~ 10.92)." (PMID 34082746, 2021).
ischemic stroke (continued). "It is also interesting to note that when analysis was repeated for ischemic stroke and CE with no history of AF in our study, ApoB association remained stronger for CE, reflecting a difference in relation to atherosclerotic strokes and etiologies." (PMID 34772344, 2021). "Moreover, recent studies have identified several predisposing genes that are also corelated with an ischemic stroke risk, such as LTC4S, ALOX5, APOA1, APOB." (PMID 33808851, 2021). "The estimate for ischemic stroke was partly attenuated after adjusting for ApoB or LDL-C." (PMID 33924871, 2021). "However, there is little research on the relationship between ApoB gene and ischemic stroke in Chinese people." (PMID 29416768, 2018). "In the Atherosclerotic Risk in Communities (ARIC) study, investigators reported weak and inconsistent [nonlinear] associations between LDL, HDL, triglycerides, ApoB, and ApoA-I with ischemic stroke risk." (PMID 20028534, 2009). "Thus, this deficit in antioxidant protection might be the pathomechanism of ischemic stroke in ICAS in patients with high apoB/apoA-I ratios." (PMID 32622367, 2020). "That also proved that regardless of whether participants had or did not have ischemic stroke, apoB/AI ratio was still an independent risk factor for ICAS." (PMID 31479420, 2019). "The ApoB/ApoA1 ratio and cholesterol in medium size HDL were particularly of importance to understand the shared pathophysiology of CHD, HF and ischemic stroke and thus should be further investigated for the prevention of all three CVDs." (PMID 38724583, 2024). "The LPS-NC, LPS-binding protein (LBP), soluble CD14 (sCD14), lipoprotein profiles, apo(lipoprotein) A-I, apoB, and phospholipid transfer protein (PLTP) activity, were determined in 98 ischemic stroke patients and 100 age- and sex-matched controls." (PMID 32084157, 2020). "No MR study has examined the associations of AA with apolipoprotein B (ApoB), an increasingly recognized predominant lipid trait in IHD and ischemic stroke, adiposity, inflammation or coagulation, or examined sex differences." (PMID 33924871, 2021). "Whether there is a cooperative action between apoB/AI ratio and ICAS on ischemic stroke needs further investigation." (PMID 31479420, 2019). "The height, weight, BMI, systolic blood pressure, glucose, pulse pressure, serum LDL-C, TG and TC levels were significantly lower; and serum HDL-C and ApoA1 levels, the ApoA1/ApoB ratio, and the proportion of drinkers were significantly higher in controls than in CAD and ischemic stroke patients." (PMID 31429711, 2019). "In addition, we observed that ApoB, ApoA1, and their ratio had a significant difference for PD-coronary events but not PD-ischemic stroke." (PMID 36008425, 2022). "However, in the MR analysis adjusted for variables, the association between the ApoB/ApoA1 ratio and PAD, cerebrovascular diseases (including TIA and ischemic stroke), non-rheumatic valve diseases, atrial fibrillation and atrial flutter diseases were significantly weakened (all P>0.05)." (PMID 38310324, 2024). "Recent MR suggested that ApoB, rather than LDL-C, is the key lipid trait in the etiology of IHD and ischemic stroke." (PMID 33924871, 2021). "Six candidate proteins (LBP, VCAM1, FCN2, FBLN1, APOC-I, and APOB) were assessed using individual samples from the CAD and non-CAD ischemic stroke subjects." (PMID 32508734, 2020). "Several recent studies noted that the lower HDL-C levels and increased ratio of the ApoA1/ApoB and serum TG, LDL-C, TC levels in smokers compared to non-smokers, all of these were related to the development of CAD and ischemic stroke." (PMID 31429711, 2019). "For the first time, differential expressions of apolipoprotein B, apolipoprotein C-I, lipopolysaccharide-binding protein, vascular cell adhesion molecule 1, fibulin-1, and ficolin-2 were confirmed as being significantly upregulated in CAD as compared to non-CAD ischemic stroke subjects." (PMID 32508734, 2020).
steatosis (55 papers, 2007 to 2026). Increased lipid within the cytoplasm of cells. "In total, we identified 27 genes, of which 3 are monogenic causes of steatosis (APOB, G6PC1, PPARG), 4 were previously associated with MASLD (APOB, APOC3, INSR, PPARG), and 23 had supporting clinical, experimental, and/or genetic evidence." (PMID 40065360, 2025). "The conditional liver-specific HNF4α disruption in mice led to severe steatosis and reduced serum triglycerides, which were associated with the selective disruption of ApoB and MTTP genes’ expression." (PMID 36362837, 2022). "APOB mutation is associated with some human cancer types such as steatosis, liver, hypocholesterolemia." (PMID 29170526, 2017). "For example, patients with hypobetalipoproteinemia, who have low plasma VLDL levels due to genetic abnormalities in the ApoB molecule, are susceptible to steatosis." (PMID 25970332, 2015). "This is the first demonstration that an abnormality in the intracellular ApoB degradation mechanism can cause steatosis, and provides a useful model for periportal steatosis, which occurs in several human diseases." (PMID 25970332, 2015). "To determine whether loss of APOB gene might cause steatosis, we measured TG levels in Ako cells by Oil Red O staining and after total lipid extraction." (PMID 40712734, 2025). "Drugs that target VLDL production or transport after ER-related post-translational regulation could potentially circumvent the steatosis associated with the degradation of apoB by ERAD." (PMID 37095219, 2023). "Therefore, the restoration of MTTP and ApoB mRNA levels by GSEE treatment also can also act as an inhibitory mechanism of HFD-caused steatosis." (PMID 33187321, 2020). "We believe that the improvement in steatosis is mainly caused by the direct effect of MDM2 inactivation on ApoB expression and TG‐VLDL secretion, whereas the alleviation of inflammation and fibrosis may be secondary to the relief from lipotoxicity in hepatocytes." (PMID 35524581, 2022). "After Bonferroni correction, we observed higher steatosis grade among APOB carriers (N = 12) compared to the matched controls (N = 45, p‐value = 0.0028)." (PMID 41514510, 2026). "Human fetal hepatocyte organoids model NAFLD steatosis under three triggers: fatty acid overload, PNPLA3 I148M mutation, and APOB/MTTP mutations." (PMID 40475995, 2025). "Reduced ApoB levels in the livers of StarD5−/− mice, coupled with increased triglyceride synthesis, appear to be able to drive steatosis in StarD5−/− mouse livers." (PMID 38591148, 2024). "For the FFA model, WT organoids were first made steatotic with a fixed concentration of FFAs (500 μM) for 3 days before drug administration, to induce a degree of steatosis similar to that observed in APOB−/− and MTTP−/− organoids." (PMID 36823355, 2023). "Liver-specific conditional knockout of HNF4α in adult mice led to severe steatosis associated with disruption of VLDL secretion and misregulation of ApoB and MTTP expression." (PMID 31781248, 2019). "Circulating PCSK9 has also been found to be significantly associated with hepatic expression of SREBP‐1c and FASN, whereas PCSK9 mRNA levels have been found to be significantly correlated with steatosis severity and hepatic APOB, SREBP‐1c, and FASN expression." (PMID 28827398, 2017). "Those patients with HCV infection who manifest steatosis, are also more likely to present hypobetalipoproteinemia (diminished serum levels of apoB bearing lipoproteins) and diminished serum cholesterol levels." (PMID 23698400, 2013). "In contrast, APOB females exhibited a surprising reduction in Leap2 expression, which may contribute to their resistance to steatosis." (PMID 40855499, 2025). "The lower expression of APOB could contribute to the steatosis in Pi*ZZ AATD patients, as it has been similarly described for APOA1 and APOF in NAFLD." (PMID 37569847, 2023).
steatosis (continued). "Here we use human fetal hepatocyte organoids to model the first stage of NAFLD, steatosis, representing three different triggers: free fatty acid loading, interindividual genetic variability (PNPLA3 I148M) and monogenic lipid disorders (APOB and MTTP mutations)." (PMID 36823355, 2023). "iPSC-derived hepatocytes are used to identify small molecule inhibitors of apoB secretion by the liver without causing steatosis." (PMID 37095219, 2023). "Finally, we leveraged the APOB- and MTTP-mutant organoids to establish a CRISPR-based screening platform to identify steatosis modulators/targets and to evaluate NAFLD risk genes." (PMID 36823355, 2023). "CD36 deletion aggravates steatosis by impairing the secretion of hepatic TG and ApoB." (PMID 35405926, 2022). "Finally, the role of ER stress in decreased apoB secretion and steatosis was further strengthened by our observation that TUDCA partially prevented these deleterious effects when cells were treated with tunicamycin, ALLO, INDO and RIF." (PMID 32535746, 2021). "To investigate whether the different apoB mutants develop steatosis, we utilized Nile red staining, which labels polar lipids in red and neutral lipids in green." (PMID 34236046, 2021). "Nevertheless, the results of this study show for the first time that a defect in a degradation mechanism of ApoB after lipidation could lead to steatosis." (PMID 25970332, 2015). "Indeed, serum levels of apolipoprotein B (ApoB) and cholesterol are reduced in chronic hepatitis C, especially in patients with steatosis and genotype 3: successful antiviral therapy results in the correction of these anomalies." (PMID 25522003, 2014). "The clinical evidence that HCV infected patients with severe steatosis have reduced serum levels of cholesterol and of apoB is consistent with the hypothesis of a possible involvement of MTP." (PMID 20178560, 2010). "Coupled with reduced ApoB expression and correct VLDL synthesis, over a prolonged period the loss of ultradian oscillations could increase the risk of developing non-alcoholic fatty liver and steatosis phenotypes." (PMID 34375333, 2021). "All of the proposed hypotheses focus on complex interactions between HCV proteins, lipid synthesis, oxidative stress, lipid peroxidation, insulin resistance and the assembly and secretion of apoB-lipoproteins, all of which might ultimately contribute to the onset of steatosis." (PMID 20178560, 2010). "While we have established APOA1 as a key functional regulator in OA-induced steatosis, the precise transcriptional regulatory relationship between APOA1 and downstream genes such as ACACA, FASN, CPT1, and APOB remains to be fully elucidated." (PMID 41463887, 2025). "Both APOB−/− and MTTP−/− mutants constitute natural steatosis organoid models that can, like their WT counterparts, be long-term expanded in culture for at least 2 years with stable steatosis levels." (PMID 36823355, 2023). "To better understand the potential role of β-catenin as a molecular determinant through which Ex-4 mediates its beneficial effect on steatosis, we quantified the expression of FABP1, FOXA1, and ApoB after β-catenin silencing." (PMID 35140289, 2022). "However, we have previously shown that miR-30c reduces apoB secretion without causing steatosis." (PMID 35278429, 2022).